DCN (decorin)
Diseases named in the same sentence as DCN in open-access papers (continued):
Sharing a sentence is not in itself a finding about the gene and the disease.
Ehlers-Danlos syndrome (10 papers, 2012 to 2024). The Ehlers–Danlos syndromes (EDS) are a clinically and genetically heterogeneous group of heritable connective tissue disorders (HCTDs) characterized by joint hypermobility, skin hyperextensibility, and tissue fragility. "Deficiency in DCN is believed to contribute to skin abnormalities such as bruising, hyperelasticity, and Ehlers-Danlos syndrome, a group of hereditary connective tissue disorders." (PMID 39199288, 2024). "A reduction in decorin levels has been found in wound healing models such as keloids, a variant of Ehlers-Danlos syndrome chronic skin ulcer and in the skin upon ultraviolet light exposure." (PMID 22479366, 2012). "Mice deficient in biglycan display a mild muscular dystrophy, and, along with mice deficient in decorin, are models of Ehlers-Danlos Syndrome, a connective tissue anomaly associated with uterine rupture." (PMID 22253749, 2012). "Loss of the dermatan sulfate of decorin leads to an Ehlers-Danlos syndrome characterized by delayed wound healing." (PMID 23226541, 2012). "The absence of DS synthesis can also have detrimental consequences on collagen architecture and tissue function, as deficiency in DS substitution of decorin due to mutation in a glycosyl transferase gene has been associated with the progeriod form of Ehlers-Danlos syndrome (EDS)." (PMID 28412940, 2017). "The DCN-BGN double-KO phenotype is reminiscent of a specific subtype of Ehlers-Danlos syndrome (EDS), the progeroid variant, a clinically and genetically heterogeneous connective tissue disorder characterized by skin hyperextensibility, joint hypermobility, and tissue fragility." (PMID 26697491, 2015). "As a variant of Ehlers-Danlos Syndrome is caused by a genetic mutation resulting in abnormal biglycan and decorin secretion, we hypothesized that biglycan and decorin play a role in uterine function." (PMID 22253749, 2012). "Another study showed that DCN and BGN double-knockout (KO) mice directly resemble the rare progeroid variant of human Ehlers-Danlos syndrome (EDS), in which skin fragility and progeroid changes in the skin (reduced hypodermis) are dramatically displayed." (PMID 32063855, 2019). "The knockout mouse of decorin exhibited irregular collagen morphology and similar phenotypes of the human Ehlers-Danlos syndrome (EDS)." (PMID 28346368, 2017).
myocardial infarction (10 papers, 2017 to 2025). Gross necrosis of the myocardium, as a result of interruption of the blood supply to the area, as in coronary thrombosis. "In the cardiovascular system, DCN deficiency results in larger infarct size, enhanced ventricular remodeling and reduced ventricular function in DCN-/- mice 2 weeks after acute myocardial infarction." (PMID 33365011, 2020). "Animal studies further indicate that decorin contributes to ventricular remodeling following acute myocardial infarction and is essential for appropriate fibrotic development in infarcted myocardium." (PMID 40697980, 2025). "In the present study, we found that DCN, which was exclusively expressed in cardiac fibroblasts, was remarkably elevated in the serum after myocardial infarction." (PMID 34621191, 2021). "Decorin and lumican are increased in myocardial fibrosis following pressure overload or myocardial infarction, while syndecan-4 contributes to myofibroblast differentiation in these settings." (PMID 32731636, 2020). "Recently it was documented that certain amount of decorin is produced in the scar tissue, the border zone close to the infarction, as well as in remote region of pig hearts after myocardial infarction." (PMID 32731559, 2020). "In conclusion, the small leucine-rich proteoglycan decorin exerts cardiocytoprotective effects against SI/R, suggesting a therapeutic potential of exogenously administered decorin for the treatment of acute myocardial infarction." (PMID 32731559, 2020). "The role of decorin has previously been studied in a chronic model of myocardial infarction showing increased concentrations within the scar, border zone and the remaining viable myocardium after 8 weeks post-MI51." (PMID 28883544, 2017). "Additionally, gene therapy using decorin has shown potential in attenuating cardiac dysfunction, positioning it as a promising therapeutic target for myocardial infarction." (PMID 40697980, 2025). "Although pre-clinical or clinical studies have linked DCN with myocardial infarction or cardiac dysfunction, there are no data on the diagnostic value of serum DCN in ACS patients." (PMID 34621191, 2021). "Therefore, in this study, we aimed to compare the serum DCN level between ACS patients and control subjects and to elucidate the inflammatory response of DCN during myocardial infarction." (PMID 34621191, 2021). "Recent studies have demonstrated that post-infarction gene therapy with adenoviral vector expressing decorin mitigates cardiac remodeling and dysfunction suggesting promising therapeutic potential of exogenous decorin for the treatment of acute myocardial infarction." (PMID 32731559, 2020). "Decorin has been shown to be involved in the ventricular remodeling following acute myocardial infarction and to be required for the proper fibrotic evolution of myocardial infarctions." (PMID 32731559, 2020). "By acting as an endogenous inhibitor of TGF-β, DCN attenuates ECM deposition and fibrosis in myocardial infarction and glomerulonephritis models." (PMID 34621191, 2021). "In the heart, lack of decorin did not influence fibrosis in healthy myocardium (despite some effect on collagen ultrastructure), but influenced scar formation after myocardial infarction." (PMID 40616270, 2025).
myeloma (9 papers, 2010 to 2024). "In accordance with independent reports, high expression of CXCL12 and DCN by myeloma cells was associated with improved OS (adj." (PMID 38598843, 2024). "We evaluated the correlation between the decorin levels measured by enzyme-linked immunosorbent assay in BM plasma from 121 patients with newly diagnosed myeloma based on their clinical features and treatment response." (PMID 26379028, 2015). "In support of this concept, low levels of DCN in cancers are associated with significantly poorer outcome and a shorter time to progression than with patients expressing higher levels of DCN in breast, lung, and soft tissue cancers as well as in myeloma." (PMID 26697491, 2015). "Another study investigated the role of decorin in multiple myeloma BM microenvironment and observed that myeloma cells decrease decorin secretion of osteoblasts and propose an indirect antagonistic action of decorin on myeloma cells." (PMID 34838648, 2022). "Another study also found osteoblast function was mediated by CCL3 in multiple myeloma in which multiple myeloma cells decreased osteoblast-induced decorin secretion." (PMID 31330786, 2019). "Multiple myeloma induced suppression of decorin in osteoblasts was found to be mediated by chemokine (C-C motif) ligand-3 (CCL3)." (PMID 29867053, 2018). "When decorin was reduced in osteoblasts, this promoted multiple myeloma cell proliferation and survival." (PMID 29867053, 2018). "First, decorin confers direct anti-myeloma effects by binding to several receptors on the MCs, such as Met, EGFR, and IGF-IR, which consequently degrades the receptors and downregulates downstream signaling, thereby inhibiting cell growth." (PMID 26379028, 2015). "Myeloma cells secrete CCL3 chemokine that suppresses DCN expression in the surrounding bone marrow stroma because stromal/osteoblast derived DCN is known to inhibit myeloma cell proliferation and survival." (PMID 26697491, 2015). "We recently demonstrated that mature osteoblasts negatively affect growth of myeloma cells and that this effect is partially mediated through production of decorin." (PMID 21188144, 2010). "Differentiating osteoblasts and BMSCs expressed high levels of decorin, especially during osteoblast differentiation, but when co-cultured with multiple myeloma cells, decorin expression decreased, which is thought to be due to decreased osteoblast differentiation." (PMID 31330786, 2019). "Osteoclasts from multiple myeloma patients expressed decreased amount of decorin, but exogenously adding decorin to a differentiating culture of precursor osteoclasts yielded a decrease in the number of TRAP positive osteoclasts, suggesting that decorin inhibits osteoclast differentiation." (PMID 31330786, 2019). "Intracellular accumulation of truncated decorin was found to induce ER stress, which may potentiate the anti-myeloma effect of PIs." (PMID 26379028, 2015). "Thus, the present study evaluated the correlation between decorin levels in the BM plasma and clinical features and treatment outcome in 121 patients with newly diagnosed multiple myeloma (NDMM) to explore the possible roles of decorin in MM." (PMID 26379028, 2015). "Together, the expression of adhesion or BM retention–related markers (CXCL12, DCN, and TGM2) is reduced or lost at advanced stages of multiple myeloma, which could enhance dissemination and reduce retention in the BM microenvironment." (PMID 38598843, 2024). "The demonstration that decorin inhibited HGF-induced viability and migration of myeloma cell lines in vitro suggests that deregulation of the physiological crosstalk among decorin, HGF, and c-MET could have a role in disease pathogenesis." (PMID 35582373, 2021). "Decorin was produced by osteoblasts, but not by multiple myeloma cells, suggesting that decorin is an inhibitory molecule for multiple myeloma survival in the bone microenvironment." (PMID 31330786, 2019).
myeloma (continued). "The reduced or total absence of DCN expression has been reported to take place in breast, colon, prostate, vascular, and bladder cancers, liposarcomas, myelomas, and malignant peripherial nerve sheath tumors." (PMID 26697491, 2015). "However, the role of decorin in patients with myeloma is not clear." (PMID 26379028, 2015). "Therefore, although the anti-myeloma effect of decorin could be (synergistically) enhanced by novel-agent based treatment, a similar effect between decorin and the chemotherapeutic agents could not be totally excluded." (PMID 26379028, 2015).
osteoarthritis (9 papers, 2008 to 2025). A noninflammatory degenerative joint disease occurring chiefly in older persons, characterized by degeneration of the articular cartilage, hypertrophy of bone at the margins and changes in the synovial membrane. "Only decorin exhibited a consistent increase in fragmentation in menisci in association with osteoarthritis." (PMID 18620607, 2008). "Together, these findings provide a mechanistic foundation for developing decorin-based biomaterials or gene therapies aimed at preserving or regenerating the cartilage matrix for improved outcomes in osteoarthritis." (PMID 41292731, 2025). "In osteoarthritis (OA), the small proteoglycans (PG), decorin and biglycan, are lost from the surface of articular cartilage; however, their contents increase in the deeper parts of the cartilage." (PMID 32353084, 2020). "Decorin degradation has been described in inflammatory diseases involving destruction of connective tissues, such as periodontitis and osteoarthritis." (PMID 24023624, 2013). "Furthermore, in vitro studies on the progression of post-traumatic osteoarthritis indicate that decorin plays a more important role than biglycan in regulating cartilage degeneration, and biglycan is more important for regulating subchondral bone structure." (PMID 41465591, 2025). "This review summarizes the role of decorin in diseases including IBD, SS, COPD, IgA nephropathy, MS, IIM, RA, and osteoarthritis." (PMID 36033387, 2022). "Inhibitors of WNT (DKK3 and FRZB), and antagonists of BMP/TGFβ (CD109, CHRDL2, DCN FMOD, INHBA and THBS1) signalling were decreased or absent in the aged inner region, consistent with the reported upregulation of these pathways in IDD and its closely related condition osteoarthritis." (PMID 33382035, 2020).
breast tumors (8 papers, 2006 to 2024). "Altered expression of decorin and lumican is associated with breast tumors." (PMID 19036156, 2008). "Thereafter, we have localized decorin mRNA in tissues samples of normal human breast and selected human breast tumors using ISH with DIG-labeled decorin probes." (PMID 23007289, 2013). "Regarding decorin, its expression has been shown to be increased in the peritumoral stroma of the malignant lesions but decreased within the breast tumor tissue." (PMID 23007289, 2013). "Next, we localized decorin mRNA in healthy human breast tissue, and in benign and selected types of malignant human breast tumors." (PMID 23007289, 2013). "ISH of healthy human breast tissue and selected human breast tumor samples revealed that decorin mRNA can merely be localized to the normal stroma." (PMID 23007289, 2013). "In previous studies, it has been demonstrated that decorin expression is high in normal human breast tissue stroma adjacent to lobules and reduced in the breast tumor itself." (PMID 23007289, 2013). "Likewise, a significant decrease in the level of DCN was previously observed within the stroma of various solid tumors including breast tumors." (PMID 38667295, 2024). "Three commonly predicted targets of the miR-17/92 cluster showing anti-correlated expression are tumor suppressors TGFBR2, DCN, and CAV1 which were under-expressed in the breast tumor tissues." (PMID 27213017, 2016).
keloid (8 papers, 2007 to 2025). An irregularly shaped, elevated mark on the skin caused by deposits of excessive amounts of collagen during wound healing. "Some proteoglycans such as biglycan and decorin are aberrantly produced in keloids, leading to an abnormal collagen architecture." (PMID 39373734, 2025). "Increasing expression of decorin by adenovirus in keloid fibroblasts significantly decreased collagen synthesis and stimulated the transcription level of MMP-1 and MMP-3." (PMID 34768882, 2021). "In situ cross-sections of keloid tissue and the monolayer cells derived from keloid tissue were positive for matrix assembly-related markers including DCN, FMOD, TGF-β1, and TGF-β3." (PMID 32085797, 2020). "DS/CS-mediated binding to TG2 has biological relevance as can be observed from our finding that the decorin molecules that are secreted by the human keloid fibroblasts into a culture medium can interact with this protein via their GAG moiety." (PMID 28199387, 2017). "To corroborate the biological occurrence of a TG2 interaction with DS/CS, we studied the co-immunoprecipitation of the enzyme with decorin, which was secreted into the culture medium by keloid fibroblasts." (PMID 28199387, 2017). "Of particular interest, 32 kDa and 45 kDa decorin fragments were identified in human keloid tissue of similar size to GrB-derived fragments." (PMID 22479366, 2012). "Collectively, these results indicate that DCN may be a potential therapeutic agent for keloids and hypertrophic scars." (PMID 32063855, 2019). "Interestingly, basic fibroblast growth factor (bFGF) can up-regulate BGN while suppressing DCN expression in keloid fibroblasts." (PMID 32063855, 2019). "In this regard, the findings on the expression of decorin, TGF-β1, and CTGF may evidence the onset of a regulatory process designed to prevent keloid formation." (PMID 38397163, 2024). "The expression of many components of ECM including collagens, decorin, versican, fibromodulin, intergrins, extracellular matrix protein 1 (ECM-1), syndecan and ESM-1 has been identified in leiomyomas as well as dermal wounds during healing, scars and keloids." (PMID 17718906, 2007).
liver cancer (8 papers, 2014 to 2024). An epithelial or non-epithelial malignant neoplasm that arises from the liver. "In the present study, we found that the expression levels of two proteoglycans, decorin and lumican, were both significantly positively associated with β-defensin 1 expression, and reduced in liver cancer." (PMID 29042578, 2017). "In this context, Decorin, a small leucine-rich proteoglycan of the extracellular matrix, has been established as a tumor suppressor gene important in the prevention of liver cancer." (PMID 34641286, 2021). "Liver cancer specimens had a significantly lower level of DCN in GSE25097 (P < 0.001), GSE14520 (P < 0.001) and GSE36376 (P < 0.001) compared to non-tumor specimens." (PMID 29042578, 2017). "Specifically, four HRGs, decorin (DCN), DNA damage inducible transcript 4 (DDIT4), protein kinase C alpha (PRKCA), and N-myc downstream regulates gene-1 (NDRG1), were included in the hypoxic risk model for liver cancer that the researchers created." (PMID 38911968, 2024). "In conclusion, our results suggest that decorin plays a protective role in liver cancer." (PMID 32477937, 2020). "In addition, decorin expression seems to follow the BCLC (Barcelona Clinic Liver Cancer) staging classification as significantly decreased decorin level was observed in every BCLC stage compared to normal liver (p < 0.001), and its level gradually decrease from BCLC 0 to BCLC B (p < 0.05 and 0.01)." (PMID 32477937, 2020). "On the other hand, the two proteoglycan genes, DCN and LUM, were both downregulated in liver cancer." (PMID 29042578, 2017). "As β-catenin activity was modulated by decorin while HGS has been shown to be required for survival in β-catenin activated background, the role of β-defensin 1 plays in β-catenin-mediated liver cancer development with this decorin- β-catenin-HGS axis warrant further confirmation and investigation." (PMID 29042578, 2017).